GNRHR (gonadotropin releasing hormone receptor)
Description:
Receptor for gonadotropin releasing hormone (GnRH) that mediates the action of GnRH to stimulate the secretion of the gonadotropic hormones luteinizing hormone (LH) and follicle-stimulating hormone (FSH). This receptor mediates its action by association with G-proteins that activate a phosphatidylinositol-calcium second messenger system. Isoform 2 may act as an inhibitor of GnRH-R signaling.
Synonyms: GRHR; LHRHR; GNRHR1; HH7; LRHR
Tractability: Small molecule: an approved drug acts on it; a structure with a bound ligand is known; a high-quality ligand is known; it belongs to a druggable protein family. Antibody: its Gene Ontology location is reachable by antibodies, with high confidence; UniProt places it where antibodies can reach, with medium confidence; UniProt predicts a signal peptide or a membrane-spanning region. PROTAC: a small molecule that binds it is known. Other modalities: an approved drug acts on it.
Target class: GnRH receptor; Short peptide receptor (family A GPCR); Family A G protein-coupled receptor; Membrane receptor; Peptide receptor (family A GPCR)
Chemical probes: BAY-784 (high quality), CHEMBL460480
Gene: Protein-coding gene on chromosome 4 (67,737,118 to 67,754,388, reverse strand). Ensembl gene ENSG00000109163.
Subcellular location: Cell membrane
Pathways (Reactome):
Signal Transduction: G alpha (q) signalling events; Hormone ligand-binding receptors
Gene Ontology:
Molecular function: gonadotropin-releasing hormone receptor activity; G protein-coupled receptor activity; protein-hormone receptor activity
Biological process: cellular response to hormone stimulus; G protein-coupled receptor signaling pathway; gonadotropin secretion; cellular response to gonadotropin-releasing hormone
Cellular component: membrane; plasma membrane
Genetic constraint (gnomAD): Loss-of-function variants: 5 observed, 13.33 expected, observed/expected ratio (o/e) 0.38, 90% interval 0.19 to 0.79. The upper end of that interval is the gene's LOEUF score, 0.79, which puts it in group 3 of 6, group 1 being the genes least tolerant of losing a copy. Missense variants: 216 observed, 222.1 expected, observed/expected ratio (o/e) 0.97, 90% interval 0.87 to 1.09. Synonymous variants: 81 observed, 84.62 expected, observed/expected ratio (o/e) 0.96, 90% interval 0.8 to 1.15.
Homologues: Orthologues: chimpanzee GNRHR (99% identical), macaque GNRHR (97% identical), dog GNRHR (92% identical), rabbit GNRHR (91% identical), mouse Gnrhr (89% identical), guinea pig GNRHR (85% identical), tropical clawed frog gnrhr2/nmi (42% identical), zebrafish gnrhr1 (41% identical), Caenorhabditis elegans gnrr-1 (30% identical), Drosophila melanogaster AkhR (29% identical). Paralogues in human: AVPR1A (25% identical), OXTR (25% identical), AVPR1B (23% identical), AVPR2 (21% identical), GPR150 (21% identical), CCKAR (20% identical), CCKBR (20% identical), GPR22 (19% identical), GALR1 (19% identical), FFAR4 (18% identical), NPFFR1 (18% identical), HCRTR2 (18% identical), and 4 more.
Diseases named in the same sentence as GNRHR in open-access papers:
GNRHR is named in the same sentence as 132 diseases in open-access papers, as found by Europe PMC text mining. Sharing a sentence is not in itself a finding about the gene and the disease. The quoted sentences say what the papers report.
prostate carcinoma (42 papers, 2009 to 2026). A carcinoma that arises from epithelial cells of the prostate gland. "This study aimed to evaluate HS1002's anticancer activity and its effects on the gonadotropin-releasing hormone receptor (GnRHR) and hTERT in prostate cancer cells." (PMID 41700173, 2026). "Degarelix is a gonadotropin-releasing hormone GnRHR antagonist used in prostate cancer patients requiring androgen deprivation therapy." (PMID 41347146, 2025). "Targeted GnRHR has been shown to be an effective treatment for prostate cancer and offers potential for combination treatment." (PMID 41347146, 2025). "Overexpression of the gonadotropin-releasing hormone receptor (GnRH-R) plays a vital role in the advancement of reproductive malignancies such as ovarian, endometrial, and prostate cancer." (PMID 39861098, 2024). "These include the gonadotropin-releasing hormone receptor antagonist Degarelix for advanced prostate cancer and the SMO receptor inhibitors Sonidegib and Vemurafenib for basal cell carcinoma." (PMID 37588995, 2023). "For example, leuprolide is a peptide drug that targets the gonadotropin-releasing hormone receptor, and it is used in the treatment of prostate cancer, while goserelin is a clinically available synthetic peptide drug for treating breast and prostate cancers." (PMID 35890274, 2022). "Leuprorelin acetate, an indole gonadotropin-releasing hormone receptor (GnRHR) agonist, is primarily used to treat prostate cancer and breast cancer." (PMID 36104717, 2022). "To answer this question, we investigated the binding affinity of our conjugates to the human pituitary GnRHR and prostate cancer GnRHR." (PMID 31717403, 2019). "The binding potency of crizotinib–GnRH conjugates to human pituitary GnRHR and prostate cancer GnRHR was investigated by a ligand competition assay." (PMID 31717403, 2019). "Currently, chronically administered gonadotropin-releasing hormone receptor (GnRH-R) agonists, which induce androgen deprivation, represent the primary clinical tools used for treating prostate cancer." (PMID 30123188, 2018). "Degarelix is a gonadrotropin-releasing hormone (GnRH) receptor (GnRHR) antagonist used in patients with prostate cancer who need androgen deprivation therapy." (PMID 25811175, 2015). "We studied the association between breast cancer risk and polymorphisms in genes that code for GNRH1 and its receptor (GNRHR) in the large National Cancer Institute Breast and Prostate Cancer Cohort Consortium (NCI-BPC3)." (PMID 19640273, 2009). "GnRHR is overexpressed in hormone-related cancers (e.g., 80% of ovarian cancer, 85% of endometrial cancer, 50% of breast cancer, and 86% of prostate cancer), as well as hormone-unrelated cancers (e.g., melanoma, glioblastoma, lung cancer and pancreatic cancer)." (PMID 40563508, 2025). "Most drug discovery attempts targeting the HPG axis for prostate cancer have focused on GnRHR." (PMID 41347146, 2025). "Collectively, these observations suggest a new paradigm that GnRHR-driven inactivation of the YAP1-AR axis could be a therapeutic target for prostate cancer." (PMID 34743733, 2021). "The current in vitro study shows that treatment of prostate cancer cells with goserelin-conjugated gold nanorods (gGNRs) promotes gonadotropin releasing hormone receptor-mediated internalization and enhances radiosensitivity to both Er-filtered and standard 250 kVp beams, 14 and 10%, respectively." (PMID 29273727, 2017). "In addition, 97.5% of breast cancers, 79.1% of endometrial cancers, and 97.1% of prostate cancers in the TCGA datasets also expressed GnRHR, suggesting that GnRHR targeting may be effective in other hormone-related tumors." (PMID 32185134, 2020). "For this reason, antagonists of GnRHR are approved and used widely for therapy of BPH and prostate cancer (PCa)." (PMID 33539321, 2021).
prostate carcinoma (continued). "Key search terms included: “G protein-coupled receptor”, “GPCR”, “prostate cancer”, “prostate carcinoma”, “castration-resistant”, “orphan receptor”, “chemokine receptor”, “CXCR4′′, “CXCR7′′, “hormone receptor”, “GnRHR”, “therapeutic target”, and “drug discovery”." (PMID 41347146, 2025). "Protein or mRNA expression of GnRH and GnRHR was detected not only in pituitary cells but also in extra-pituitary cells; ovarian, breast, prostate tissues, and various cancer cell lines including breast (MCF-7 and MDA-MB-468) and prostate cancer (PCa) cells (PC-3 and LNCaP)." (PMID 34743733, 2021).
breast carcinoma (26 papers, 2006 to 2025). "In conclusion, we can exclude the possibility that common polymorphisms in GNRH1 and GNRHR confer large or even moderate breast cancer risks in Caucasians." (PMID 19640273, 2009). "We hypothesized that common, functional polymorphisms of GNRH1 and GNRHR could influence breast cancer risk by modifying production of FSH/LH and steroid hormones." (PMID 19640273, 2009). "It was also reported that GnRH/GnRHR system suppressed the invasiveness of the highly invasive breast cancer cell line MDA-MB-231." (PMID 35011543, 2022). "Expression of gonadotropin releasing hormone receptor (GnRH-R) on breast carcinoma cells is reported to be higher than those on the normal breast tissue." (PMID 23472175, 2013). "In the present study, we analyzed the molecular mechanisms employed by the human GnRHR to regulate cell motility in the highly invasive breast cancer cell line MDA-MB-231." (PMID 23176180, 2012). "Nevertheless, the IP response was considerably reduced (by ~80%) in cells transfected with the empty vector, thus reflecting the low levels of endogenously expressed GnRHR in MDA-MB-231 breast cancer cells." (PMID 23176180, 2012). "Nevertheless, at this point much less is known about the molecular mechanisms subserving the effects of the GnRH/GnRHR system to inhibit breast cancer cells migration." (PMID 23176180, 2012). "Our data are consistent with previous studies in MCF-7 breast cancer cells, in which the GnRH/GnRHR system was capable to selectively promote IP production." (PMID 23176180, 2012). "Among members of the GPCR family, gonadotropin-releasing hormone receptor (GnRH) has been reported to be overexpressed in various tumor cells such as melanoma, prostate and endometrial cancer, leiomyoma, breast cancer, choriocarcinoma, epithelial ovarian tumor, and stromal ovarian tumor." (PMID 35307012, 2022). "GnRHR activation could induce apoptosis and G2/M arrest and played an anti-proliferative role in breast cancer." (PMID 35011543, 2022). "In addition, tissues of malignant tumors, such as breast cancer, ovarian cancer and endometrial cancer, experience high affinity of GnRHR expression as well." (PMID 27845755, 2016). "Based on these results, we conclude that common polymorphisms in GNRH1 and GNRHR do not substantially affect breast cancer risk in Caucasians." (PMID 19640273, 2009). "Among pathways, the gonadotropin-releasing hormone receptor pathway, ubiquitin proteasome pathway, CCKR signaling map, and integrin signalling pathway are shown to be involved in breast cancer." (PMID 29589558, 2018). "In fact, the increased expression levels and IP response to GnRHa detected in GnRHR-transfected MDA cells, emulated those previously detected in breast cancer cells exhibiting high GnRHR expression levels." (PMID 23176180, 2012). "In the present study, we provide evidence demonstrating that in the highly invasive human breast cancer MDA-MB-231 cell line, activation of the GnRHR promotes RhoA activation, actin cytoskeleton remodeling and a remarkable increase in cell adhesion to substrate." (PMID 23176180, 2012).
ovarian carcinoma (21 papers, 2009 to 2025). A malignant neoplasm originating from the surface ovarian epithelium. "The overexpression of gonadotropin-releasing hormone (GnRH) receptor (GnRHR) in ovarian cancers makes it an effective theranostic target." (PMID 40563508, 2025). "Our previous studies have also confirmed the overexpression of GnRHR in the majority of ovarian cancer samples." (PMID 40563508, 2025). "First, we evaluated the accumulation of GnRHa-PEG-Rh760 in primary tumors using a mouse model bearing subcutaneous A2780 (GnRHR-positive) ovarian cancer." (PMID 40563508, 2025). "Our previous study confirmed the overexpression of GnRHR in ovarian cancer and the binding capacity of the GnRHa peptide to ovarian cancer cells." (PMID 40563508, 2025). "Experiments in different ovarian cell types, as well as in several ovarian cancer lines, have shown in addition to GnRHR protein expression, the presence of GnRHR mRNA transcripts and the presence of binding sites for the GnRH ligand." (PMID 37958948, 2023). "In a mouse ovarian cancer model, local administration of the gonadotropin-releasing hormone receptor (GNRHR)-targeted peptide EP-100 was combined with anti-PD-L1-generating NK cell, DC and CD8 T cell tumour infiltration." (PMID 34733287, 2021). "To evaluate the relevance of GnRHR as an imaging target in human ovarian cancer, we first analyzed 373 cases of serous ovarian cancer from TCGA datasets." (PMID 32185134, 2020). "It is well established that GnRHR is overexpressed in ovarian cancer and other hormone-related cancers, even in some hormone-unrelated cancers (pancreatic cancer, lung cancer, melanoma, and glioblastoma)." (PMID 32185134, 2020). "GnRHa-ICG showed specific binding capacities to GnRHR-positive cancer cells and effectively distinguished peritoneal metastases from adjacent normal tissue in ovarian cancer mouse models." (PMID 32185134, 2020). "This study aimed to develop a GnRHR-targeted near-infrared imaging probe for the detection of peritoneal metastases of ovarian cancer." (PMID 32185134, 2020). "Estradiol (E2) downregulated the expression of GnRHR and reduced GnRHR-mediated inhibition of proliferation in the ovarian cancer cell line, OVCAR-3." (PMID 28439256, 2017). "In another study, the GnRHR agonist, [d-Ala6] GnRH, directly inhibited the growth of ovarian cancer cells in a time- and dose-dependent manner, whereas a GnRHR antagonist (Antide) reversed this effect." (PMID 28439256, 2017). "FSHR or GnRHR targeted agents have been developed by using corresponding ligands, and phase II studies have shown their promising applications for ovarian cancer." (PMID 28122595, 2017). "Because GnRHR is expressed in the ovary, it is widely believed to be involved in ovarian cancer development and metastasis." (PMID 28439256, 2017). "In vitro experiments also support this relationship as treatment with a specific GnRHR agonist (Buserelin) inhibited phosphatidylinositol kinase and exhibited a strong anti-mitogenic effect on ovarian carcinoma cells." (PMID 28439256, 2017). "Transcriptomic and proteomic approaches were used to investigate the effects of triptorelin, an agonist of GnRHR, on ovarian cancer cells." (PMID 28439256, 2017). "Gonadotropin-releasing hormone receptor signaling stimulates ovarian cancer cell attachment to mesothelial cells in part by inducing P-cadherin that is expressed in ovarian cancer cells and in mesothelial cells." (PMID 24567915, 2014). "GnRHR expression in KGN cells is similar to that of two ovarian cancer cell lines with demonstrated responsiveness to GnRH." (PMID 23372819, 2013). "How these compounds influence other major receptors (e.g. gonadotropin receptor and GnRHR) mediated signal cascades in the ovarian cancer cell is a key question to be clarified in the future investigations." (PMID 21617769, 2011). "A promising target for ovarian cancer is the gonadotropin-releasing hormone receptor (GnRHR)." (PMID 32185134, 2020).
ovarian carcinoma (continued). "In summary, the developed GnRHR-targeting imaging agent binds selectively to ovarian cancer." (PMID 32185134, 2020). "In this study, we introduced GnRHR as the target for the molecular imaging of ovarian cancer." (PMID 32185134, 2020). "The expression of GnRHR in ovarian cancer tissue is higher than that in normal ovarian tissue." (PMID 32185134, 2020). "Collectively, these data suggested that GnRHR could be a potential imaging target for the detection of ovarian cancer." (PMID 32185134, 2020). "Having demonstrated the specific binding capacity of GnRHa-ICG in ovarian cancer, we speculate that our GnRHR imaging concept might also be effective in other tumors with upregulated GnRHR expression." (PMID 32185134, 2020). "In conclusion, GnRHR is a critical regulator of ovarian cancer cell proliferation." (PMID 28439256, 2017). "The potential role of GnRHR as a tumor suppressor in ovarian cancer has been hypothesized because ovarian cancer patients with lower tumor expression levels of GnRHR showed more favorable survival rates." (PMID 28439256, 2017). "Furthermore, GnRH-activated receptor (GnRHR) induces the activation of p38 kinase and AP-1, and decreases the Erk function to inhibit proliferation of ovarian cancer cells." (PMID 21617769, 2011). "Here, we report the development and validation of a GnRHR-targeted NIR fluorescent probe, GnRHa-PEG-Rh760, as a tool for the intraoperative specific fluorescence imaging of metastatic lymph nodes in ovarian cancer." (PMID 40563508, 2025). "In summary, this study successfully developed a GnRHR-targeted NIR fluorescent probe, which illuminated primary tumors, peritoneal metastases and lymph node metastases of ovarian cancer with high specificity in preclinical models." (PMID 40563508, 2025). "Because the role of GPER in OVACR-3 and hOSE cell proliferation and migration is unclear, further studies are required to explore the potential cross talk between GnRHR and GPER in regulating ovarian cancer progression." (PMID 28439256, 2017). "Two human ovarian cancer cell lines, CaOV3 and OVCAR3, were used as positive controls because we have previously demonstrated that they express GnRHR." (PMID 23372819, 2013). "In this study, we synthesized and characterized a GnRHR-targeted NIR fluorescent probe, GnRHa-PEG-Rh760, and demonstrated its specific binding and imaging capabilities for primary tumors, peritoneal metastases, and lymph node metastases in ovarian cancer." (PMID 40563508, 2025).